MIR4424 (microRNA 4424)
Synonyms: hsa-mir-4424
Gene: MicroRNA gene on chromosome 1 (178,677,749 to 178,677,834, forward strand). Ensembl gene ENSG00000266417.
Homologues: Orthologues: chimpanzee MIR4424 (100% identical).